OR7G3 (olfactory receptor family 7 subfamily G member 3)
Description:
Odorant receptor.
Synonyms: OST085
Tractability: Antibody: UniProt places it where antibodies can reach, with medium confidence; UniProt predicts a signal peptide or a membrane-spanning region; its Gene Ontology location is reachable by antibodies, with medium confidence.
Gene: Protein-coding gene on chromosome 19 (9,126,012 to 9,126,950, reverse strand). Ensembl gene ENSG00000170920.
Subcellular location: Cell membrane
Pathways (Reactome):
Sensory Perception: Expression and translocation of olfactory receptors
Gene Ontology:
Molecular function: olfactory receptor activity; G protein-coupled receptor activity; signaling receptor activity
Biological process: signal transduction; detection of chemical stimulus involved in sensory perception of smell; G protein-coupled receptor signaling pathway; sensory perception of chemical stimulus
Cellular component: plasma membrane; membrane
Genetic constraint (gnomAD): Missense variants: 350 observed, 388.09 expected, observed/expected ratio (o/e) 0.9, 90% interval 0.83 to 0.99. Synonymous variants: 142 observed, 165.35 expected, observed/expected ratio (o/e) 0.86, 90% interval 0.75 to 0.99.
Homologues: Orthologues: chimpanzee OR7G3 (96% identical), dog OR7G3 (83% identical), mouse Or7g12 (78% identical), rat Or7g12 (76% identical), mouse Or7g19 (75% identical). Paralogues in human: OR7G2 (68% identical), OR7G1 (66% identical), OR7A10 (64% identical), OR7D4 (64% identical), OR7C1 (63% identical), OR7A17 (62% identical), OR7A5 (62% identical), OR7C2 (62% identical), OR7D2 (62% identical), OR7E24 (60% identical), OR1G1 (54% identical), OR1J4 (54% identical), and 116 more.